Y_RNA (Y RNA )
Gene: Miscellaneous RNA gene on chromosome 11 (3,665,164 to 3,665,259, reverse strand). Ensembl gene ENSG00000200201.
Homologues: Orthologues: chimpanzee Y_RNA (100% identical). Paralogues in human: RNY4 (86% identical), RNY4P6 (85% identical), RNY4P9 (85% identical), RNY4P7 (84% identical), RNY4P10 (83% identical), RNY4P19 (83% identical), RNY4P24 (83% identical), RNY4P25 (83% identical), Y_RNA (83% identical), RNY4P13 (82% identical), RNY4P14 (82% identical), RNY4P3 (82% identical), and 87 more.